FGGY (FGGY carbohydrate kinase domain containing)
Description:
Catalyzes ATP-dependent phosphorylation of D-ribulose at C-5 to form D-ribulose 5-phosphate. Postulated to function in a metabolite repair mechanism by preventing toxic accumulation of free D-ribulose formed by non-specific phosphatase activities. Alternatively, may play a role in regulating D-ribulose 5-phosphate recycling in the pentose phosphate pathway. Can phosphorylate ribitol with low efficiency.
Synonyms: FLJ10986
Tractability: PROTAC: ubiquitination databases record sites on it.
Gene: Protein-coding gene on chromosome 1 (59,295,910 to 59,810,647, forward strand). Ensembl gene ENSG00000172456.
Subcellular location (Human Protein Atlas): Nucleoplasm; Nuclear bodies
Gene Ontology:
Molecular function: D-ribulokinase activity; kinase activity; phosphotransferase activity, alcohol group as acceptor
Biological process: carbohydrate phosphorylation; neuron cellular homeostasis; pentose metabolic process; carbohydrate metabolic process
Cellular component: cytoplasm
Genetic constraint (gnomAD): Loss-of-function variants: 49 observed, 51.8 expected, observed/expected ratio (o/e) 0.95, 90% interval 0.75 to 1.2. The upper end of that interval is the gene's LOEUF score, 1.2, which puts it in group 5 of 6, group 1 being the genes least tolerant of losing a copy. Missense variants: 573 observed, 630.07 expected, observed/expected ratio (o/e) 0.91, 90% interval 0.85 to 0.97. Synonymous variants: 220 observed, 235.34 expected, observed/expected ratio (o/e) 0.93, 90% interval 0.84 to 1.04.
Homologues: Orthologues: chimpanzee FGGY (99% identical), macaque FGGY (97% identical), dog FGGY (93% identical), mouse Fggy (91% identical), rat Fggy (91% identical), guinea pig FGGY (90% identical), pig FGGY (81% identical), tropical clawed frog fggy (69% identical), Drosophila melanogaster CG11594 (50% identical), zebrafish fggy (46% identical). Paralogues in human: GK (20% identical), GK3 (20% identical), GK2 (19% identical), GK5 (19% identical), SHPK (19% identical), XYLB (14% identical).
Diseases named in the same sentence as FGGY in open-access papers:
FGGY is named in the same sentence as 9 diseases in open-access papers, as found by Europe PMC text mining. Sharing a sentence is not in itself a finding about the gene and the disease. The quoted sentences say what the papers report.
Obesity (3 papers, 2019 to 2022). Accumulation of substantial excess body fat. "FGGY is known to encode a protein that phosphorylates carbohydrates and is associated with obesity and sporadic amyotrophic lateral sclerosis." (PMID 32850797, 2020). "FGGY gene is associated with amyotrophic lateral sclerosis, and FGGY mRNA is stronger in mouse WATs than in brown adipose tissue and is enhanced in gonadal fat by diet-induced obesity." (PMID 31341893, 2019). "LINE-1 retrotransposons suppress FGGY, leading to lipid metabolism disturbance and diet-induced obesity in mice." (PMID 32850797, 2020). "Besides that, FGGY can regulate dietary obesity in mice by regulating lipid metabolism." (PMID 35842613, 2022).
amyotrophic lateral sclerosis (2 papers, 2019 to 2025). Amyotrophic lateral sclerosis (ALS) is a neurodegenerative disease characterized by progressive muscular paralysis reflecting degeneration of motor neurons in the primary motor cortex, corticospinal tracts, brainstem and spinal cord. "Both DPP6 and FGGY genes have been associated with an increased susceptibility for sporadic amyotrophic lateral sclerosis." (PMID 39857271, 2025).
sporadic amyotrophic lateral sclerosis (2 papers, 2015 to 2022). Sporadic amyotrophic lateral sclerosis is a amyotrophic lateral sclerosis in which there is no known cause, such as no family history. "FGGY expression has been recently associated with an increased susceptibility to sporadic amyotrophic lateral sclerosis." (PMID 24934327, 2015). "FGGY was first reported to be related with sporadic amyotrophic lateral sclerosis." (PMID 35842613, 2022).
Coronary artery atherosclerosis (1 paper, 2025). "Coronary artery atherosclerosis (LAD-lesion area) was positively correlated with WDR62 and MARS1 transcript levels, and negatively correlated with FGGY, PAQR8, and RPS20 transcript levels (p < 0.05)." (PMID 40709334, 2025).
lung squamous cell carcinoma (1 paper, 2022). "As the host gene of circFGGY, it was recently reported that FGGY was a novel tumor suppressor gene and disruption of FGGY gene could promote the development and progression of lung squamous cell carcinoma." (PMID 35592246, 2022).
tumor (3 papers, 2022 to 2023). "LINE-1 retrotransposition can affect local immune homeostasis by interfering with the expression of the tumor suppressor gene FGGY in squamous lung cancer and disrupting cellular energy metabolism, leading to tumor progression and poor prognosis." (PMID 37546391, 2023). "The increased secretion levels of 12S-HETE was detected in H520OV−L1−FGGY vs H520OV−CTRL cell lines and further validated in 50 LUSC tissues compared to matched adjacent normal tissues as well as L1-FGGY+ vs FGGY− tumor tissues." (PMID 35842613, 2022). "Interestingly, FGGY is involved with arachidonic acid metabolism and regarded as a putative tumor suppressor gene." (PMID 35842613, 2022). "L1-FGGY interferes with the tumor suppressor function of FGGY, thereby, promotes cancer cell proliferation, invasion and accelerated tumor growth corresponding with a tumor microenvironment deplete of immune cell populations to forge a cytotoxic response to tumor cells." (PMID 35842613, 2022).
FGGY also shares sentences with these, for which no sentence is quoted: cancer (2 papers); hepatocellular carcinoma (1); lung adenocarcinoma (1).